GSDME (gasdermin E)
Diseases named in the same sentence as GSDME in open-access papers (continued):
Sharing a sentence is not in itself a finding about the gene and the disease.
acute myeloid leukemia (2 papers, 2022 to 2025). Acute myeloid leukemia (AML) is a group of neoplasms arising from precursor cells committed to the myeloid cell-line differentiation. "Talabostat 22 is pyrrolidine derivative that triggers pyroptosis in acute myeloid leukemia cells by activating caspase-1 and GSDME." (PMID 39316325, 2025).
amyotrophic lateral sclerosis (2 papers, 2025 to 2026). Amyotrophic lateral sclerosis (ALS) is a neurodegenerative disease characterized by progressive muscular paralysis reflecting degeneration of motor neurons in the primary motor cortex, corticospinal tracts, brainstem and spinal cord. "In other conditions, Gasdermin E cleavage has been shown to be partly responsible for pyroptotic cell death in human immunodeficiency virus-associated neurocognitive disorder and in amyotrophic lateral sclerosis." (PMID 40331993, 2025). "By causing mitochondrial damage in axons, GSDME activation could hasten the progression of frontotemporal dementia (FTD) and amyotrophic lateral sclerosis (ALS)." (PMID 41574659, 2026).
brain tumor (2 papers, 2021 to 2024). "Intriguingly, the GSDME mRNA was highly expressed in brain tumor, NB, and pleura among 34 tumor types." (PMID 38177154, 2024).
clear cell renal cell carcinoma (2 papers, 2024). "We also analyzed proteomic data from the CPTAC database to explore the expression of GSDME in clear cell renal cell carcinoma (ccRCC) tissues." (PMID 39119834, 2024).
Cognitive impairment (2 papers, 2023). Abnormal cognition is characterized by deficits in thinking, reasoning, or remembering. "Our previous research demonstrated that SNAP25 mitigated surgery-induced cognitive impairment by enhancing PTEN-induced kinase 1 (PINK1)/Parkin-dependent mitophagy as well as repressing caspase-3/gasdermin E (GSDME)-dependent pyroptosis." (PMID 38102610, 2023). "The role of GSDMD and GSDME-mediated pyroptosis in cognitive impairment have been elucidated, but the mechanisms of other gasdermin family members such as GSDMA, GSDMB, GSDMC and DFNB59 in cognitive impairment remained unclear." (PMID 37332874, 2023). "Functional investigations further revealed that neuron-specific inhibition of TNFAIP1 alleviated postoperative cognitive disorders by intensifying PINK1/Parkin-dependent mitophagy and suppressing caspase-3/GSDME-dependent pyroptosis." (PMID 38102610, 2023). "Taken together, these findings support the idea that TNFAIP1 silencing mitigates postoperative cognitive impairment, intensifies PINK1/Parkin-mediated mitophagy and restrains caspase-3/GSDME-mediated pyroptosis by stimulating SNAP25 protein expression." (PMID 38102610, 2023).
colorectal tumors (2 papers, 2023 to 2025). "We found that the transcriptional levels of GSDMA, GSDMC, and PJVK were significantly increased in human colorectal tumors; while, the expression of GSDMB, GSDMD, and GSDME remained unchanged." (PMID 40213993, 2025).
dermatitis (2 papers, 2022 to 2024). An inflammatory process affecting the skin. "Given that UVB-induced skin inflammation is the core mechanism in the pathogenesis of UV-associated skin disorders, GSDME function in immune cells recruited into UV-challenged skin should be deeply explored." (PMID 36182937, 2022). "In IMQ-induced psoriasis-like dermatitis mice, full length, and cleavage of caspase-3 and GSDME were notably increased." (PMID 38429278, 2024). "Furthermore, Gsdme knockout (KO) mice (Gsdme-/- mice) and keratinocyte-specific Gsdme conditional knockout (cKO) mice were used to explore the role of GSDME in psoriasis-like dermatitis." (PMID 38429278, 2024).
diabetes (2 papers, 2023 to 2024). "In summary, our findings reveal TNFSF15 is a natural brake on GSDME-triggered retinal cell pyroptosis induced by diabetes." (PMID 38331883, 2024).
diabetic retinopathy (2 papers, 2022 to 2024). "Collectively, our results demonstrate TNFSF15 inhibits diabetic retinopathy progression by blocking GSDME-dependent pyroptosis of retinal cells, suggesting the TNFSF15-GSDME interaction as a promising therapeutic target for diabetic retinopathy." (PMID 38331883, 2024). "We found GSDME was upregulated in the progression of diabetic retinopathy." (PMID 38331883, 2024). "This study explored the role of GSDME-mediated pyroptosis and its regulation by TNFSF15 in diabetic retinopathy." (PMID 38331883, 2024). "In this study, we confirmed that high glucose could upregulate the expression of caspase-3 and GSDME in the diabetic model, suggesting that CASP3-mediated pyroptosis is involved in the development of diabetic retinopathy, which has not been explored." (PMID 35957838, 2022).
gastric tumors (2 papers, 2022 to 2023). "GSDME methylation was detected in primary gastric tumors, and exogenous expression of GSDME in cell with GSDME silencing inhibited colony formation." (PMID 37679782, 2023).
H1N1 influenza (2 papers, 2025). "Here, we investigated the role of GSDME in two distinct models of severe H1N1 influenza using Gsdme−/− mice." (PMID 40766393, 2025). "H1N1 virus infection dose- and time dependently induced GSDMD and GSDME cleavage in these two cell lines, which generated a truncated N-terminal fragment with a molecular mass around 30 and 34 kDa, respectively." (PMID 39811662, 2025).
hearing disorder (2 papers, 2021 to 2023). A disorder characterized by the partial or complete loss of the ability to detect sounds due to damage to the ear structures or inability of the brain to properly interpret or process the auditory signals it receives from the anatomic structures of the ear. "GSDME was originally recognized as one mutated gene (DFNA5), which leads to hearing disorders, contributed by loss of cochlear hair loss." (PMID 38016064, 2023).
intestinal cancer (2 papers, 2019 to 2020). "In this study, we evaluated the tumor-suppressive effects of GSDME in two intestinal cancer mouse models." (PMID 31434357, 2019). "In this study, we aimed to evaluate the tumor-suppressive effects of GSDME in two intestinal cancer mouse models." (PMID 31434357, 2019). "Deep proteomic analysis of a panel of 50 intestinal cancer cell lines shows that caspase-4 and GSDMD are constitutively expressed, while NLR family pyrin domain containing 3 (NLRP3), gasdermin E (GSDME), and caspase-5 are undetectable under standard growth conditions." (PMID 33378358, 2020).
intestinal tumors (2 papers, 2022 to 2023). "Further, considering the new perspectives on pyroptosis, we found that QCWZD can inhibit GSDME-mediated pyroptosis to prevent the occurrence of intestinal tumors." (PMID 35910578, 2022).
kidney injury (2 papers, 2021). Trauma to the kidney. "Due to the parallel level of GSDME-N and some other pyroptotic characteristics, GSDME-mediated pyroptosis might be a pathogenic mechanism influencing cisplatin-induced kidney injury." (PMID 33542198, 2021). "Deletion of gasdermin E (GSDME), an executor of pyroptosis, has been reported to suppress renal tubular cell pyroptosis in several models of kidney injury." (PMID 34746148, 2021).
leukemia (2 papers, 2022 to 2023). A malignant (clonal) hematologic disorder, involving hematopoietic stem cells and characterized by the presence of primitive or atypical myeloid or lymphoid cells in the bone marrow and the blood. "Additionally, reduced expression of GSDME was significantly associated with decreased event-free survival in leukemia patients, as determined by analysis with Kaplan‒Meier Plotter." (PMID 37679782, 2023). "The potential prognostic value of GSDME expression in patients with leukemia patients was investigated using the R2 and Kaplan‒Meier Plotter databases." (PMID 37679782, 2023).
myeloma (2 papers, 2025 to 2026). "In multiple myeloma (Multiple Myeloma, MM)), proteasome inhibitor PIs can trigger pyroptosis of myeloma cells (Myeloma cells) through the mitochondrial BAX/GSDME pathway and improve the therapeutic efficiency of multiple myeloma treatment." (PMID 40671910, 2025). "In addition, similar to GSDME, FOXO3 is also downregulated in MM and its restoration suppresses myeloma tumor growth." (PMID 41694578, 2026).
osteoarthritis (2 papers, 2021). A noninflammatory degenerative joint disease occurring chiefly in older persons, characterized by degeneration of the articular cartilage, hypertrophy of bone at the margins and changes in the synovial membrane. "Pyroptosis has recently been shown to promote knee osteoarthritis, and upregulation of Gsdme in high-grade osteoarthritis cartilage, supports a role for gasdermin E in disease progression." (PMID 33473114, 2021).
periodontitis (2 papers, 2022 to 2024). An acute or chronic inflammatory process that affects the tissues that surround and support the teeth. "Another study indicated that GSDME-mediated macrophage pyroptosis is implicated in periodontitis." (PMID 39742284, 2024). "Meanwhile, the increased trimethylamine-N-oxide in periodontitis patients damages peripheral endothelial progenitor cells through pyroptosis driven by Bax/caspase-3/GSDME pathway, suggesting that GSDME activation may also be associated with endothelial dysfunction in periodontitis patients." (PMID 35462927, 2022). "Recent study has shown that pyroptosis plays a significant role in the pathogenesis of periodontitis, particularly through GSDME-mediated macrophage pyroptosis." (PMID 39742284, 2024). "Additionally, GSDME, another member of the gasdermin family, facilitates macrophage pyroptosis through O-GlcNAcylation induced by high glucose levels in the context of periodontitis." (PMID 39742284, 2024). "Furthermore, it was demonstrated that GSDME was significantly upregulated in patients with periodontitis and in macrophages treated with HG and LPS." (PMID 39742284, 2024). "Therefore, GSDME-mediated pyroptosis is correlated to periodontal inflammation such as peri-implantitis and periodontitis." (PMID 35462927, 2022).
pulmonary arterial hypertension (2 papers, 2025 to 2026). Pulmonary arterial hypertension (PAH) is a group of diseases characterized by mean pulmonary artery pressure >20 mmHg and elevated pulmonary arterial resistance leading to right heart failure. "Interestingly, ET-1-induced expression of GSDME was restrained by macitentan, a non-selective ETAR/ETBR antagonist approved by regulatory agencies for the therapy of pulmonary arterial hypertension." (PMID 41545335, 2026).
silicosis (2 papers, 2022 to 2025). Silicosis is a respiratory disease caused by breathing in (inhaling) silica dust. "The results showed that the cleavage of GSDMD and GSDME were significantly enhanced in silicosis patients." (PMID 36459518, 2022). "For example, in silicosis, caspase-1-mediated cleavage of gasdermin D (GSDMD) and caspase-3/8-mediated cleavage of gasdermin E (GSDME) drive pyroptotic cell death." (PMID 40384344, 2025).
acute lymphocytic leukemia (1 paper, 2021). "According to previous research, GSDME is expressed in Burkitt's lymphoma cell line Raji and the acute lymphocytic leukemia (ALL) cell line Nalm-6." (PMID 34522213, 2021).
Arthritis (1 paper, 2022). Inflammation of a joint. "In the case of GSDME, its deficiency leads to protection against collagen-induced arthritis." (PMID 35455985, 2022). "This early study highlights a possible role of GSDME in triggering arthritic pathology in murine collagen-induced arthritis but remains to be validated by others and further mechanistically explored." (PMID 35455985, 2022). "The role of GSDME in collagen-induced arthritis has also been investigated in one study." (PMID 35455985, 2022).
aspiration pneumonitis (1 paper, 2024). Inflammation of the lungs due to the inhalation of solid or liquid material. "To confirm that the phenotype observed in KO mice was mediated by GSDME disruption in neutrophils, we also induced aspiration pneumonitis in Mrp8-cre(+)/GsdmeΔ/Δ and Mrp8-cre(-)/Gsdmefl/fl littermates." (PMID 38195694, 2024).
Atrophy (1 paper, 2023). Any weakening or degeneration, especially through lack of use. "In particular, GSDME-deficiency significantly attenuated the hippocampal atrophy and changed levels of DAM markers in GCLC-KO mice." (PMID 36670138, 2023).
breast ductal adenocarcinoma (1 paper, 2023). A breast carcinoma arising from the ducts. "In patients with breast ductal adenocarcinoma, a negative correlation was observed between the degree of GSDME methylation and 5-year overall survival (OS), indicating that GSDME methylation is a prospective biomarker for determining prognosis." (PMID 38104141, 2023).
chlamydia infection (1 paper, 2023). "In this study, we confirmed that chlamydia infection could upregulate the expression of caspase-3 and GSDME in the lung, suggesting that caspase-3 is involved in pyroptosis in Chlamydia trachomatis infection, which is worthy of further exploration." (PMID 37686375, 2023).
Cholestatic liver disease (1 paper, 2025). "Caspase-3 inhibitors, such as Ac-DMPD/DMLD-CMK, effectively block gasdermin E (GSDME)-mediated pyroptosis, suggesting potential therapeutic applications in cholestatic liver disease." (PMID 41153801, 2025).
co-infection (1 paper, 2025). "Further studies incorporating co-infection models, high-resolution transcriptomic approaches, or long-term follow-up of infected mice may be necessary to fully define subtle or context-dependent roles of GSDME in H1N1 IAV infections." (PMID 40766393, 2025).
colorectal adenocarcinoma (1 paper, 2019). The most common type of colorectal carcinoma. "We postulate that the methylation of GSDME could serve as a worthy biomarker for the detection of colorectal adenocarcinomas." (PMID 30993897, 2019).
corneal disease (1 paper, 2023). "Overall, these findings support a role for NLRP3 and caspase-1 in regulating bacterial killing and corneal disease severity with no apparent role for NLRC4 and no requirement for GSDMD, GSDME, or neutrophil elastase." (PMID 37730693, 2023).
dementia (1 paper, 2022). Loss of intellectual abilities interfering with an individual's social and occupational functions. "The number of GSDME positive cells was increased, and the hippocampal CA3 region was found neuronal degeneration and cell death after disposing with methamphetamine (METH, a dementia simulant), indicating that GSDME-mediated pyroptosis occurred in hippocampal neurons." (PMID 35782390, 2022).
diphtheria (1 paper, 2025). A Gram-positive bacterial infection caused by Corynebacterium diphtheriae. "We demonstrate that GSDME cleavage is not required for secondary necrosis downstream of caspase activation and suggest that caspase inhibition may hold promise as a therapeutic option for the treatment of diphtheria." (PMID 41185624, 2025).
endometrial cancer (1 paper, 2025). Primary or metastatic malignant neoplasm involving the endometrium (mucous membrane that lines the endometrial cavity).
epilepsy (1 paper, 2021). A brain disorder characterized by episodes of abnormally increased neuronal discharge resulting in transient episodes of sensory or motor neurological dysfunction, or psychic dysfunction. "GSDMD and GSDME, the key executive molecules of pyroptosis, will help to understand the pathogenesis of epilepsy and aid in discovering new targets for anti-epileptic drug treatments." (PMID 35095728, 2021). "We established a mouse model of kainic acid-induced epilepsy to verify the expression of GSDMD and GSDME at the transcriptome and protein levels." (PMID 35095728, 2021). "Consistent with the results of bioinformatics analysis, qRT-PCR results also confirmed that the mRNA expression of GSDME was not different between the epilepsy group and sham group." (PMID 35095728, 2021). "The mRNA expression of GSDME was not different between the epilepsy group and sham group." (PMID 35095728, 2021). "However, it is worth noting that GSDMD and GSDME, as the executioner of pyroptosis, has not been studied in epilepsy thus far." (PMID 35095728, 2021).
hyperandrogenism (1 paper, 2025). Excessive secretion of androgens from the adrenal glands or gonads. "In PCOS, the IL2RG/GSDME axis interacts with key pathways: hyperandrogenism signals through IL-2R, activating CASP3 which cleaves GSDME." (PMID 40830889, 2025).
Hyperglycemia (1 paper, 2022). An increased concentration of glucose in the blood. "In the current study, both GSDMD and GSDME were increased in the high-glucose-treated retinal vascular endothelial cells, which is consistent with previous findings, indicating that hyperglycemia can trigger pyroptosis in retinal vascular endothelial cells." (PMID 35957838, 2022).
hypertriglyceridemia (1 paper, 2025). A laboratory test result indicating elevated triglyceride concentration in the blood. "In addition, fold change in GSDME expression between lesions and normal skin was, significantly, 2.4 times lower in patients with hypertriglyceridemia and tended to be 2.5 times lower in the case of insulin resistance." (PMID 41007405, 2025).
injury (1 paper, 2025). Damage inflicted on the body as the direct or indirect result of an external force, with or without disruption of structural continuity. "Defects in Gasdermin-E (GSDME) reverse CPS1 degradation mediated by deISGylation, alleviating ammonia accumulation and suggesting a promising therapeutic approach for acetaminophen-induced liver injury." (PMID 40103488, 2025).
ischemia (1 paper, 2025). A hypoperfusion of the BLOOD through an organ or tissue caused by a PATHOLOGIC CONSTRICTION or obstruction of its BLOOD VESSELS, or an absence of BLOOD CIRCULATION. "An intriguing study revealed that aerobic exercise inhibits GSDME-dependent cardiomyocyte pyroptosis, thereby effectively protecting the heart from ischemia–reperfusion injury." (PMID 41550939, 2025).
ischemic stroke (1 paper, 2022). A stroke disorder caused by obstruction of blood flow to the brain, due to thrombotic (local blood clot formation) or embolic (due to a blood clot or other material traveling from another site) event. "In sum, our results showed that PD-L1 knockout in platelet reduced the release of IL-1β through regulating Caspas-3/GSDME alleviated ischemic stroke and thrombotic cerebral vascular occlusions with significantly better neurological effects and survival rates after tMCAO." (PMID 35784685, 2022).
keratitis (1 paper, 2023). A corneal disease that is characterized by inflammation of the cornea. "As there was no role for GSDMD or GSDME in P. aeruginosa keratitis, and as these bacteria induce NETs in murine models of pulmonary and corneal infections, we examined if this is related to NETosis induced by P. aeruginosa." (PMID 37730693, 2023).
lung fibrosis (1 paper, 2025). "In this study, we first demonstrated that cleaved GSDME levels were increased in the lungs of mice with aPD-1 + BLM-induced lung fibrosis." (PMID 39762211, 2025). "Notably, the mice with pulmonary fibrosis that were treated with SP600125 exhibited reduced protein expression levels of GSDME." (PMID 39762211, 2025). "We also revealed the significant involvement of GSDME-mediated pyroptosis in the pathogenesis and development of ICI-LI and demonstrated that the JNK inhibitor SP600125 can alleviate lung fibrosis by inhibiting GSDME-mediated pyroptosis." (PMID 39762211, 2025).
lymphoproliferative disorders (1 paper, 2019). "Since GSDME is induced and cleaved during glucocorticoid-induced apoptosis, it is therefore likely that GSDME plays important physiological roles in determining the fate of developing thymocytes, the progression of lymphoproliferative disorders, or immune responses to stress." (PMID 30976076, 2019).
meningococcal disease (1 paper, 2022). "On a clinical point of view, induction of caspase-3 / GSDME-dependent pyroptosis may well be involved in the inflammation characteristic of invasive meningococcal disease." (PMID 35765029, 2022).